KIF2B (kinesin family member 2B)
Description:
Plus end-directed microtubule-dependent motor required for spindle assembly and chromosome movement. Has microtubule depolymerization activity. Plays a role in chromosome congression.
Tractability: PROTAC: ubiquitination databases record sites on it; its protein half-life has been measured.
Gene: Protein-coding gene on chromosome 17 (53,822,927 to 53,825,193, forward strand). Ensembl gene ENSG00000141200.
Subcellular location: Cytoplasm, cytoskeleton, microtubule organizing center, centrosome; Cytoplasm, cytoskeleton, spindle; Chromosome, centromere, kinetochore
Subcellular location (Human Protein Atlas): Cytokinetic bridge; Microtubules; Mitotic spindle; End piece; Mid piece; Nucleoli; Principal piece
Pathways (Reactome):
Cell Cycle: Amplification of signal from unattached kinetochores via a MAD2 inhibitory signal; EML4 and NUDC in mitotic spindle formation; Mitotic Prometaphase; Resolution of Sister Chromatid Cohesion; Separation of Sister Chromatids
Hemostasis: Kinesins
Immune System: MHC class II antigen presentation
Signal Transduction: RHO GTPases Activate Formins
Vesicle-mediated transport: COPI-dependent Golgi-to-ER retrograde traffic
Gene Ontology:
Molecular function: ATP binding; microtubule binding; microtubule motor activity
Biological process: metaphase chromosome alignment; microtubule depolymerization; regulation of chromosome segregation; microtubule-based movement
Cellular component: centrosome; cytosol; kinesin complex; spindle
Genetic constraint (gnomAD): Loss-of-function variants: 13 observed, 16.73 expected, observed/expected ratio (o/e) 0.78, 90% interval 0.5 to 1.24. The upper end of that interval is the gene's LOEUF score, 1.24, which puts it in group 5 of 6, group 1 being the genes least tolerant of losing a copy. Missense variants: 908 observed, 878.43 expected, observed/expected ratio (o/e) 1.03, 90% interval 0.98 to 1.09. Synonymous variants: 370 observed, 347.78 expected, observed/expected ratio (o/e) 1.06, 90% interval 0.98 to 1.16.
Homologues: Orthologues: chimpanzee KIF2B (99% identical), macaque KIF2B (92% identical), dog KIF2B (79% identical), rabbit KIF2B (78% identical), pig KIF2B (78% identical), mouse Kif2b (78% identical), rat Kif2b (78% identical), guinea pig KIF2B (68% identical). Paralogues in human: KIF2A (58% identical), KIF2C (45% identical), KIF24 (30% identical), KIF13B (22% identical), KIF14 (22% identical), KIF7 (22% identical), KIF16B (21% identical), KIF4A (21% identical), KIF1A (21% identical), KIF4B (21% identical), KIF1B (21% identical), KIF27 (21% identical), and 29 more.
Diseases named in the same sentence as KIF2B in open-access papers:
KIF2B is named in the same sentence as 7 diseases in open-access papers, as found by Europe PMC text mining. Sharing a sentence is not in itself a finding about the gene and the disease. The quoted sentences say what the papers report.
lung carcinoma (1 paper, 2025). "The other two members of the kinesin-13 family, KIF2B and KIF24, which are also microtubule depolymerases, have been less studied in the context of lung cancer." (PMID 40002279, 2025).
medulloblastoma (1 paper, 2022). A malignant, invasive embryonal neoplasm arising from the cerebellum. "Although KIF2B was reported as an oncogene in several malignant tumor types, its role in medulloblastoma has not been studied so far." (PMID 35866054, 2022).
cancer (4 papers, 2014 to 2023). A tumor composed of atypical neoplastic, often pleomorphic cells that invade other tissues. "Indeed, the overexpression of Kif2b or MCAK, in addition to reestablishing the stability of chromosomally unstable cancer cells, inhibits metastasis in vitro and in vivo, with a consequent increase in survival." (PMID 33114575, 2020).
tumor (4 papers, 2016 to 2023). "KIF20A is one of the leading edge genes found on GSEA of M1-poly versus M0-NM DEGs and is homologous to KIF2B, a protein that directly promotes tumor metastasis in cell line models of CIN." (PMID 32380981, 2020). "After treatment with TMZ for 2 weeks, DHC2 and KIF2B expression was up-regulated in tumor xenografts." (PMID 27375225, 2016). "Tumor xenografts also demonstrated DHC2 and KIF2B up-regulation following systemic treatment of mice with TMZ." (PMID 27375225, 2016).
KIF2B also shares sentences with these, for which no sentence is quoted: gastric cancer (1 paper); glioma (1); spondylocarpotarsal synostosis syndrome (1).